NLRP12 (NLR family pyrin domain containing 12)
Diseases named in the same sentence as NLRP12 in open-access papers (continued):
Sharing a sentence is not in itself a finding about the gene and the disease.
gastric cancer (1 paper, 2025). A primary or metastatic malignant neoplasm involving the stomach. "According to TCGA data analysis, NLRP12 was significantly overexpressed in gastric cancer tissues, and high NLRP12 expression was associated with shorter disease-free survival periods." (PMID 40796546, 2025). "The experimental results indicate that the changes in proliferation, glycolysis and downstream signals of gastric cancer cells are indeed caused by the changes in NLRP12." (PMID 40796546, 2025). "An important finding of the present study was that abnormally elevated NLRP12 expression during the progression of gastric cancer is strongly associated with the regulation of abnormal proliferation of gastric cancer cells through the ubiquitination of HK2 and subsequent HK2-mediated H3K18la." (PMID 40796546, 2025). "This study is the first to show that NLRP12 in gastric cancer cells promotes gastric cancer progression through metabolic reprogramming." (PMID 40796546, 2025). "The GSE134520 dataset involves single-cell sequencing analysis of gastric cancer, and analysis of this dataset revealed that NLRP12 was expressed mainly in malignant gastric cancer cells and also partially expressed in gland mucous, pit mucous and plasma." (PMID 40796546, 2025). "Because protein stability is regulated mainly by the ubiquitin–proteasome system and the autophagy system, we treated NLRP12-overexpression gastric cancer cells with MG132, a classical ubiquitination inhibitor, and CQ, an autophagy-lysosomal pathway inhibitor." (PMID 40796546, 2025). "After knockdown of NLRP12, the overall lactate level and histone lactate level in gastric cancer cells decreased, whereas opposite effects were observed when NLRP12 was overexpressed." (PMID 40796546, 2025). "To further clarify the ability of NLRP12 to regulate the proliferation in gastric cancer cells, we constructed a tumor xenograft model in nude mice." (PMID 40796546, 2025). "The present study revealed that NLRP12 was highly expressed in gastric cancer tissues and cells, as well as positively correlated with poor patient prognosis and survival." (PMID 40796546, 2025). "The present study revealed that NLRP12 is highly expressed in gastric cancer and promotes gastric cancer development, and this ability is due mainly to its ability to promote glucose metabolism and lactic acid metabolism in gastric cancer cells." (PMID 40796546, 2025). "In summary, these data indicate that targeting HK2 disrupts NLRP12-mediated metabolic reprogramming and malignant progression in gastric cancer." (PMID 40796546, 2025). "IHC analyses confirmed that NLRP12 was specifically upregulated in gastric cancer tissues compared to adjacent normal tissues, where its expression was significantly lower." (PMID 40796546, 2025). "To evaluate the specific mechanism by which NLRP12 promotes gastric cancer in vivo, we established xenograft gastric cancer models." (PMID 40796546, 2025). "In conclusion, our findings demonstrate that NLRP12 drives gastric cancer cell proliferation via glycometabolic reprogramming, mechanistically linked to Myc transcriptional activation through H3K18la." (PMID 40796546, 2025). "To investigate the role of NLRP12 in gastric cancer progression, we used the TCGA database and the GSE134520 dataset to analyze its expression in gastric cancer tissues and adjacent normal tissues." (PMID 40796546, 2025). "Knockdown of NLRP12 significantly reduced the proliferation ability of gastric cancer cells, whereas overexpression of NLRP12 significantly enhanced the proliferation ability of gastric cancer cells." (PMID 40796546, 2025). "To further clarify that NLRP12 promotes gastric cancer proliferation through HK2-mediated glycolysis, we employed both pharmacological inhibition (2-DG, a competitive HK2 inhibitor) and genetic silencing (shRNA-mediated HK2 knockdown)." (PMID 40796546, 2025). "NLRP12 is a molecular target highly correlated with the diagnosis, treatment, and prognosis of gastric cancer." (PMID 40796546, 2025).
gastric cancer (continued). "NLRP12 promoted the progression of gastric cancer mainly by promoting the metabolic reprogramming of gastric cancer cells, the expression of histone H3 lysine 18 lactylation (H3K18la) and the stabilization of hexokinase 2 (HK2), a crucial enzyme in glycolysis." (PMID 40796546, 2025). "To evaluate the specific mechanisms by which NLRP12 regulates glycolysis and lactate production in gastric cancer cells, we investigated the enzymes involved in glycolysis." (PMID 40796546, 2025). "In gastric cancer cells, NLRP12 knockdown significantly decreased glycolysis levels and capacity, whereas NLRP12 overexpression significantly increased glycolysis levels and capacity." (PMID 40796546, 2025). "In addition, analysis of RNA and protein expression in gastric cancer and paracancerous tissues further revealed that NLRP12 was more highly expressed in gastric cancer than in paracancerous tissues." (PMID 40796546, 2025). "Therefore, we employed NLRP12 knockdown and overexpression cellular models along with xenograft mouse models to investigate the pivotal role and characteristics of NLRP12 in gastric cancer progression." (PMID 40796546, 2025). "Moreover, HK2 overexpression significantly reversed the inhibitory effect on the proliferation of gastric cancer cells induced by NLRP12 knockdown." (PMID 40796546, 2025). "To assess whether NLRP12 affects gastric cancer cell proliferation through glycolysis, we conducted Seahorse metabolic flux analysis." (PMID 40796546, 2025). "NLR family pyrin domain containing 12 (NLRP12) is related to innate immunity, inflammation and tumorigenesis, but its role in the progression of gastric cancer remains unclear." (PMID 40796546, 2025). "In summary, NLRP12 regulates the proliferation of gastric cancer cells both in vivo and in vitro." (PMID 40796546, 2025). "By screening the TCGA database, analyzing the GSE134520 single-cell sequencing data, and verifying via clinical data collection, the present study revealed that NLRP12 was highly expressed in gastric cancer cells and was positively correlated with poor patient prognosis." (PMID 40796546, 2025). "Notably, genetic perturbation of TRIM25 (knockdown or overexpression) effectively rescued the NLRP12-mediated modulation of proliferative capacity in gastric carcinoma cells." (PMID 40796546, 2025). "Because the most prevalent autophagy-targeting signal in mammals is cargo K63-linked ubiquitination, we examined the level of HK2 ubiquitination in gastric cancer cells to further investigate whether the mechanism by which NLRP12 increases the expression of HK2 protein is related to ubiquitination." (PMID 40796546, 2025). "Mechanistically, NLRP12 binds to TRIM25 to prevent TRIM25 from participating in the K63-linked ubiquitination of HK2, which subsequently enhances the protein stability of HK2, thereby upregulating the expression of HK2 and promoting glycolysis in gastric cancer cells." (PMID 40796546, 2025). "We investigated the mechanism of NLRP12 in gastric cancer and revealed the specific pathway regulating metabolic reprogramming, which may provide new targets and new ideas for gene therapy in gastric cancer." (PMID 40796546, 2025). "In summary, the present study revealed that NLRP12-mediated HK2 ubiquitination is the main mechanism to regulate glycolysis and histone lactylation in gastric cancer and is important for the progression of this disease." (PMID 40796546, 2025). "To further explore the functional role of NLRP12 in gastric cancer progression, we knocked down NLRP12 in AGS cells and overexpressed NLRP12 in MKN-45 cells, and we verified the knockdown or overexpression efficiency by RT-qPCR and Western blot analysis." (PMID 40796546, 2025). "Conversely, on NLRP12 overexpression, the HK2 protein levels in gastric cancer cells significantly increased, whereas other glycolytic enzymes did not significantly change." (PMID 40796546, 2025).
gastric cancer (continued). "NLRP12 has been widely verified as an inflammatory regulator, but its role in regulating gastric cancer has not been confirmed." (PMID 40796546, 2025). "However, the role of NLRP12 in gastric cancer has not been well studied." (PMID 40796546, 2025).
glioblastoma (1 paper, 2019). The most malignant astrocytic tumor (WHO grade IV). "Importantly, our study is the first to report a differential regulation of NLRP12 in glioblastoma with differential cell specific roles." (PMID 31186453, 2019). "Based on high significance level, we suggest NLRP12 as possible prognostic marker for glioblastoma." (PMID 31186453, 2019).
Glomerular sclerosis (1 paper, 2023). Accumulation of scar tissue within the glomerulus. "The Nlrp12–/–/lpr mice exhibited further progression to glomerular sclerosis, with 7.3% of glomeruli showing complete sclerosis during the ninth month (score 5), revealing the acceleration of disease activity under NLRP12 deficiency." (PMID 36719379, 2023).
Granuloma (1 paper, 2013). A compact, organized collection of mature mononuclear phagocytes, which may be but is not necessarily accompanied by accessory features such as necrosis. "The number of granulomas observed per lung and the average size of the granulomas were not significantly different between the Nlrp12−/− and wild type mice." (PMID 23577168, 2013).
intraepithelial neoplasia (1 paper, 2017). A precancerous neoplastic process that affects the squamous, glandular, or transitional cell epithelium without evidence of invasion. "The comparative analysis between adjacent benign, intraepithelial neoplasia (PIN) and malignant tissues for NLRP3 or NLRP12 is from the same slide of cancerous tissue." (PMID 28663562, 2017).
Klebsiella Infections (1 paper, 2022). Infections with bacteria of the genus KLEBSIELLA. "Hematopoietic-derived Nlrp12 has been reported to be important for host defense against Klebsiella infection, where bacterial clearance and neutrophil influx into the lung are dependent on Nlrp12." (PMID 35313917, 2022).
Klebsiella pneumonia (1 paper, 2021). An pneumonia caused by infection with Klebsiella. "The physiological impact of NLRP12 regulation in the immune response is still elusive, for instance, the loss of NLRP12 in BMDC induces IL-6 and TNF upon M. tuberculosis or Klebsiella pneumonia without conferring resistance against these bacteria." (PMID 34768828, 2021).
parasites infection (1 paper, 2021). "In parasites infection, NLRP12 can function in inflammasome formation and was crucial for caspase-1 activation and IL-1β production during rodent malaria infection." (PMID 34956178, 2021).
prostate (1 paper, 2017). "The selected expression of NLRP3 and NLRP12 inflammasomes was validated, and the clinical association was evaluated in human prostate archival tumor tissues." (PMID 28663562, 2017).
prostate tumors (1 paper, 2017). "We further analyzed the clinical relevance of NLRP3 and NLRP12 in archival human prostate tumor specimens using IHC." (PMID 28663562, 2017). "In contrast to the NLRP3 expression, we found that NLRP12 protein is significantly higher in human prostate tumor tissues as compared to adjacent benign tissues." (PMID 28663562, 2017). "For NLRP12, we performed IHC on 50 archival specimens of human prostate tumor tissues." (PMID 28663562, 2017).
pyoderma gangrenosum (1 paper, 2020). An idiopathic, rapidly evolving, and severely debilitating disease occurring most commonly in association with chronic ulcerative colitis. "Mutations involving different autoinflammatory genes (MEFV, NLRP3, NLRP12, NOD2, LPIN2, and PSTPIP1) have been reported in syndromic HS [pyoderma gangrenosum, acne, and hidradenitis suppurativa (PASH) syndrome] as well as in pyoderma gangrenosum (PG), a prototypic neutrophilic dermatosis." (PMID 32425927, 2020).
retinal ischemia (1 paper, 2020). A ischemic disease that involves the retina. "In the current study, we found that high IOP-induced retinal ischemia promoted the upregulation of NLRP12 and NLRC4." (PMID 32295623, 2020). "Together, these findings depict a novel function for NLRP12 in pyroptosis with regard to the pathogenesis of retinal ischemia and RGCs death, indicating that NLRP12 coordinates with NLRP3 and NLRC4 to exert both neuroinflammatory and pyroptotic effects under ischemic conditions." (PMID 32295623, 2020). "Given these novel findings, we have determined that IL-1β is a central factor enhancing CASP8-HIF-1α signaling to subsequently increase NLRP3/NLRP12/NLRC4 activation and to initiate pyroptosis during retinal ischemia." (PMID 32295623, 2020).
rheumatoid arthritis (1 paper, 2023). A chronic, systemic autoimmune disorder characterized by inflammation in the synovial membranes and articular surfaces. "For example, overexpressed NLRP12 suppressed the phosphorylation of JNK, ERK1/2, and p38 in fibroblast-like synoviocytes of rheumatoid arthritis." (PMID 37658975, 2023).
steatosis (1 paper, 2019). Increased lipid within the cytoplasm of cells. "There were significantly higher inflammatory infiltrates, steatosis, and fibrosis in Nlrp12-/- livers relative to WT." (PMID 30990169, 2019).
infection (38 papers, 2013 to 2025). The state of being infected such as from the introduction of a foreign agent such as serum, vaccine, antigenic substance or organism. "Regardless of the activation mechanism, NLRP12-driven IL-18 secretion and associated IFN-γ production play a critical role in resistance against Y. pestis infection in mice; NLRP12-deficient mice showed higher mortality and bacterial loads after infection." (PMID 38566180, 2024). "Various studies have described NLRP12 as a critical innate immune checkpoint in cancer and pathogenic infections." (PMID 34768828, 2021). "Similar findings have been reported for NLRP6 and NLRP12 to play a pathogenic role during infection with Brucella abortus, S. Typhimurium, and Plasmodium chaubadi." (PMID 34690967, 2021). "In contrast, but consistent with the results for C57BL/6J mice, NLRP12-deficient mice were highly susceptible to i.n. infection with F. tularensis LVS with >75% of NLRP12-deficient mice succumbing to infection by day 12 post infection." (PMID 27779193, 2016). "The increased susceptibility of Nlrp12−/− mice to infection with F. tularensis LVS compared with WT (C57BL/6N) mice was also reflected by increased bacterial burdens in infected organs 6 and 9 days post infection." (PMID 27779193, 2016). "We examined the induction of cytokines and chemokines in BAL fluid from WT (C57BL/6N) and NLRP12-deficient mice 3 days post infection." (PMID 27779193, 2016). "During Yersinia pestis infection, NLRP12 is reported to recognize acylated lipid A and Nlrp12−/− mice were more susceptible to infection and had reduced IL-18 levels." (PMID 24062750, 2013). "With this in mind, it would be interesting to see whether Myotis davidii would be more susceptible to SARS-CoV-2, and if IRF3 and NLRP12 levels are affected during infection, or if the unique features implicated in chiopteran tolerance for multiple viruses would still protect this species." (PMID 33372854, 2021). "Across infection, inflammatory disease, and cancer, there is accumulating evidence indicating NLRP12 as an inflammasome and PANoptosome sensor, or as an inhibitory sensor of inflammation." (PMID 39351983, 2025). "We first observed a significant downregulation of NLRP12 across different macrophage cell lines post-infection." (PMID 39119293, 2024). "A significant decrease in NLRP12 expression post-infection was observed in various macrophage cell lines." (PMID 39119293, 2024). "As an inflammasome sensor, NLRP12 initiates pyroptosis in response to infections by Yersinia pestis, Plasmodium chabaudi, and Toxoplasma gondii, which results in the secretion of IL-1β and IL-18 and a reduction in the pathogen burden." (PMID 39119293, 2024). "THP-1, a human monocytic cell line, was used to measure the change in NLRP12 expression, and infection with the RNA virus (Vesicular stomatitis virus [VSV]) and the DNA virus (Herpes simplex virus-1) downregulated NLRP12 expression." (PMID 36719379, 2023). "Further review of the literature uncovers the extensive research significance and value of PHGDH and NLRP12 in virus-infection-related studies." (PMID 38257759, 2023). "During infections, such as Yersinia pestis or Plasmodium chabaudi, NLRP12 was thought to act as a sensor to form a multiprotein complex called the inflammasome, which contains ASC and caspase‐1 and drives the cell death pathway pyroptosis." (PMID 37700491, 2023). "NLRP12 induces the production of inflammasome-dependent cytokines IL-1β/18 following Yersinia or Plasmodium salina infection, thereby preventing severe infections by these pathogens." (PMID 36189207, 2022). "In influenza A virus (IAV) infected mice, NLRP12 exacerbated the pathogenesis of infection by facilitating massive neutrophil chemotaxis via promoting CXCL1 expression." (PMID 34956178, 2021).